MOG (myelin oligodendrocyte glycoprotein)
Diseases named in the same sentence as MOG in open-access papers (continued):
Sharing a sentence is not in itself a finding about the gene and the disease.
autoimmune encephalitis (72 papers, 2014 to 2026). Inflammation of the brain secondary to an immune response triggered by the body itself. "It accounts for approximately 70%–80% (50%–60% if MOG antibody‐associated cases are included) of pediatric cases with anti‐neuronal antibody‐mediated autoimmune encephalitis." (PMID 41489316, 2026). "CAR T-cell therapy holds promise for addressing other antibody-mediated CNS disorders, e.g., MOG-associated disease or autoimmune encephalitis." (PMID 39276207, 2024). "In contrast to autoimmune encephalitis with other antibodies, normal MRI findings in MOG-IgG-associated autoimmune encephalitis are rare." (PMID 38333186, 2023). "Although there were some cohort studies about autoimmune encephalitis, MOG antibody-associated disorders (MOG-AD), or autoimmune GFAP astrocytopathy (GFAP-A), such studies involving pediatric individuals are still limited." (PMID 37153594, 2023). "MOG-IgG-associated autoimmune encephalitis, a second common pediatric manifestation, presents with large subcortical and/or cortical lesions." (PMID 38333186, 2023). "Antibody-mediated central nervous system (CNS) disorders including those associated with aquaporin-4 or myelin oligodendrocyte glycoprotein IgG and autoimmune encephalitis often affect women of childbearing age." (PMID 36601293, 2022). "Autoimmune encephalitis (AE) causes severe neurologic symptoms in patients of all ages, and advances in AE diagnosis have led to the identification of more antibodies causing brain inflammation, so antibodies to MOG and NMDAR have been reported with increasing frequency in AE." (PMID 37153679, 2023). "After that, Hikari suggested that the presence of anti-NMDAR and anti-MOG antibodies in autoimmune encephalitis is a new clinical entity." (PMID 39981240, 2025). "We suggest that upon suspicion of autoimmune encephalitis, all patients should be tested for serum and CSF anti-MOG IgG antibodies." (PMID 39479094, 2024). "The autoimmune encephalitis panel indicated positivity for serum MOG antibodies (1:10) and serum mGluR5 antibody (1:32), while a negative result was observed in CSF." (PMID 39151524, 2024). "Upon suspicion of autoimmune encephalitis, extensive laboratory testing was performed, and the patient’s serum and cerebrospinal fluid (CSF) tested positive for anti-MOG, while anti-glial fibrillary acidic protein (GFAP) antibodies were detected in her serum." (PMID 39479094, 2024). "Our case indicates that, upon suspicion of autoimmune encephalitis with clinical or neuroradiological findings indicating cortical involvement, testing for anti-MOG IgG antibodies in serum and CSF is warranted." (PMID 39479094, 2024). "One such clinical entity is myelin oligodendrocyte glycoprotein (MOG) antibody (Ab)-positive autoimmune encephalitis (AE)." (PMID 36832501, 2023). "The broader impairment of neuronal networks contributing to cognition can be assumed due to the ubiquitous brain localization of MOG antibodies, as these autoantibodies induce experimental autoimmune encephalitis." (PMID 33677623, 2021). "Three hundred ten patients with autoimmune encephalitis (AE) were also reviewed, and cases with positive MOG-ab were identified." (PMID 34691028, 2021). "In the animal model of MS, MOG-induced experimental autoimmune encephalitis in Dark Agouti rats, PEBP1 was one of the down-regulated genes in the remitting stage of this disease model." (PMID 31141529, 2019). "This study also demonstrated that the intranasal and intravenous treatment with BTN peptide can conversely abrogate MOG-induced autoimmune encephalitis." (PMID 29401697, 2018). "Additionally, a comprehensive review of the literature on autoimmune encephalitis with MOG-IgG coexistence, excluding NMDARe, was conducted." (PMID 40703404, 2025).
autoimmune encephalitis (continued). "Non-infectious etiologies must also be considered, including post-infectious and autoimmune disorders such as Bickerstaff brainstem encephalitis, myelin oligodendrocyte glycoprotein antibody-associated disease (MOGAD), and other forms of autoimmune encephalitis." (PMID 40573455, 2025). "We propose that the co-occurrence of anti-NMDAR and anti-MOG antibodies in autoimmune encephalitis represents a novel form of the condition that diverges from anti-NMDAR encephalitis or MOGAD alone and that each antibody has its own unique pathological implications." (PMID 38895128, 2024). "In addition, synergy between native gut bacteria Lactobacillus reuteri and OTU0002 Erysipelotrichaceae in the mouse can lead to intestinal T-cell responses to MOG in the CNS, potentially resulting in autoimmune encephalitis." (PMID 39775333, 2024). "We examined whether MOG1-125 conjugated with PLGA could induce MOG-specific immune tolerance in an experimental autoimmune encephalitis (EAE) mouse model." (PMID 38468222, 2024). "Thus, in an experimental autoimmune encephalitis elicited by the injection of the myelin-oligodendrocyte glycoprotein (MOG), the encephalitogenic response of Th1 and Th17 immune cells was substantially reduced in the absence of Tnc." (PMID 35681468, 2022). "In addition, pretreatment with MOG35-55 peptide-pulsed minocycline/dexamethasone-conditioned tDCs significantly ameliorated the clinical signs of experimental autoimmune encephalitis induced by MOG peptide injection in a murine model." (PMID 29118423, 2017). "Reduced expression of C/EBPδ in mice is associated with increased expression of IL10 by dendritic cells with subsequent enhancement of regulatory T-cells and less severe clinical disease when experimental autoimmune encephalitis is induced by vaccination with myelin oligodendrocyte glycoprotein." (PMID 25393235, 2014). "The pathological mechanism underlying the generation of anti-MOG antibodies in pediatric autoimmune encephalitis without demyelination is unknown." (PMID 36532000, 2022). "In recent years, the anti-MOG antibody has been reported to be associated with various types of autoimmune encephalitis (AE) without demyelination, such as cortical encephalitis, brainstem encephalitis, and even AE with normal findings on brain magnetic resonance imaging (MRI)." (PMID 36532000, 2022). "Further autoimmune encephalitis panel testing for antibodies to anti-aquaporin 4 (AQP4), anti-myelin oligodendrocyte glycoprotein (MOG), anti-N-methyl-D-aspartate receptor (NMDAR), anti-LGI1, and anti-GABABR in the patient's CSF and serum were negative." (PMID 34160439, 2021). "Based on our findings, patients with concomitantly positive MOG-Ab and anti-NMDAR antibody are a common subpopulation of autoimmune encephalitis, who can present milder disease conditions but subject to relapses." (PMID 34268281, 2021). "Concurrently, CSF and serum tests for MOG antibody and an autoimmune encephalitis panel covering antibodies against NMDA, AMPA1, AMPA2, LGI1, CASPR2, GABAB, GABAA, IgLON5, DPPX, GlyR1, DRD2, GAD65, mGluR5, mGluR1, KLHL11, AQP4, MOG, GFAP, and neurexin-3α were conducted on a cell-based assay." (PMID 39151524, 2024). "Cell-based assays for anti-aquaporin-4, anti-myelin oligodendrocyte glycoprotein, autoimmune encephalitis panel, and vasculitis workup were all negative, except for CSF positivity for GFAP α antibody." (PMID 38699059, 2024). "In this study, we evaluated the clinical characteristics of 18 pediatric patients having autoimmune encephalitis with positive MOG antibodies in the serum but without demyelination on brain MRI." (PMID 36532000, 2022). "In the two cases later diagnosed as autoimmune encephalitis, MOG-IgG testing was initially prompted by abnormalities noted on brain MRI." (PMID 35795797, 2022).
autoimmune encephalitis (continued). "In this study, the main clinical manifestations in patients having MOG antibody-positive autoimmune encephalitis without demyelination were altered mental status, prolonged fever, and headaches." (PMID 36532000, 2022). "Not all patients with suspected autoimmune encephalitis were tested for anti-MOG antibodies in our retrospective study." (PMID 36532000, 2022). "As a result, some scholars have proposed that anti-MOG antibodies may not have a direct correlation with non-demyelinating encephalitis, and there could be other autoimmune encephalitis-related antibodies coexisting with MOG antibodies." (PMID 40740785, 2025). "The transfection cytology methods were used to detect autoimmune encephalitis antibodies (NMDAR, AMPAR1, AMPAR2, LGI1, CASPR2, GABABR, DPPX, IgLON5, GlyRα1, GABAARα1, GABAARβ3, mGluR1, mGluR5, D2R, Neurexin-3α, GAD65, KLHL11, gAChR, AQP4, MOG, GFAP) in CSF and serum." (PMID 40771880, 2025). "Finally, eight patients were tested for autoimmune encephalitis antibodies or CNS demyelinating antibodies; serum myelin oligodendrocyte glycoprotein (MOG) antibody was positive in two patients and negative in six patients." (PMID 37573554, 2023). "Hence, determination of the true recurrence rate of MOG antibody-positive pediatric autoimmune encephalitis without demyelination will require a longer follow-up." (PMID 36532000, 2022). "Therefore, whether the anti-MOG antibody is the most common antibody in Asian patients having autoimmune encephalitis without demyelination needs to be confirmed in more prospective studies." (PMID 36532000, 2022). "Aquaporin 4 (AQP4), myelin oligodendrocyte glycoprotein (MOG), myelin basic protein (MBP IgG), and autoimmune encephalitis-related antibodies were negative." (PMID 39911384, 2025). "The patient tested negative for anti-myelin oligodendrocyte glycoprotein (MOG) antibodies, glial fibrillary acidic protein (GFAP), as well as other autoimmune encephalitis antibodies (anti-GABAB, anti-AMPAR1, anti-AMPAR2, anti-LGI1 and anti-CASPR2)." (PMID 35527314, 2022). "At this point, further autoimmune encephalitis antibody detection suggested that anti-NMDAR antibody IgG in CSF was positive with a titer of 1:3.2, and the serum and CSF paratumor antibodies, anti-myelin oligodendrocyte glycoprotein (MOG) autoantibodies, were negative." (PMID 37721572, 2024).
demyelination (59 papers, 2009 to 2025). "Myelin-oligodendrocyte glycoprotein antibody associated disease (MOGAD) is a common inflammatory disease of the central nervous system (CNS) in children that can lead to demyelination." (PMID 39981242, 2025). "When BBB permeability increases, such as during CNS infection, MOG-IgG enters the CNS, causing demyelination." (PMID 39845958, 2024). "Myelin oligodendrocyte glycoprotein antibody‐associated disease (MOGAD) is diagnosed by serum MOG‐immunoglobulin G (MOG‐IgG) in association with typical demyelination." (PMID 39073255, 2024). "Pathologically, perivenous inflammatory demyelination with loss of MOG-dominant myelin was a characteristic finding of MOG antibody-associated disease." (PMID 36816137, 2023). "According to the latest treatment methods for MOG-IgG-associated demyelination in children, first-line immunotherapy conventionally includes intravenous corticosteroids, IVIG, and plasma exchange (PLEX) in a single or combined form." (PMID 35669399, 2022). "Treatment of patients with MOG-Ab-associated demyelination includes management of acute relapses and chronic immunotherapy for those with relapsing disease." (PMID 30671648, 2019). "A recent study from Australia showed the clinical courses, treatments and outcomes of 59 cases (33 pediatric patients) with relapsing MOG-Ab-associated demyelination, of whom 73% were Caucasian." (PMID 31440204, 2019). "The purpose of this review is to summarize current understanding regarding the treatment of myelin oligodendrocyte glycoprotein antibody (MOG-Ab)-associated demyelination in children." (PMID 30671648, 2019). "Observations of high titers in more severe phenotypes and active disease directly support the pathogenic potential of MOG Ab in human demyelination." (PMID 31481127, 2019). "In contrast, in NMO and anti-MOG antibody-associated demyelination, a peripherally generated CNS-targeting antibody response is suggested to be the main disease driver." (PMID 30800132, 2019). "Patients with MOG-Ab-associated demyelination seem to have unique clinical and radiological features." (PMID 31440204, 2019). "Neuropathological findings in patients with myelin oligodendrocyte glycoprotein (MOG) antibody (Ab)-associated demyelination." (PMID 28533781, 2017). "Due to the predominant humoral pathogenic mechanisms, it seems rationale to treat MOG antibody associated demyelination with immune suppression including steroids, plasma exchange, or a B-cell-directed therapy, similar to NMO." (PMID 26919719, 2016). "This is the first study to report elevation of CSF cytokines and chemokines in MOG Ab-associated demyelination, and therefore investigate additional immunopathological aspects other than autoantibody-associated mechanisms." (PMID 26919719, 2016). "Unlike NMO and MS, there is a paucity of literature on immunopathology and CSF cytokine/chemokines in MOG Ab associated demyelination." (PMID 26919719, 2016). "We investigated a comprehensive array of cytokines/chemokines in our patients with seropositive and seronegative MOG Ab associated demyelination." (PMID 26919719, 2016). "Despite the increasingly available literature on MOG antibodies in CNS demyelination syndromes, the pathophysiology of the inflammatory processes underlying MOG antibody associated demyelination remains to be fully elucidated." (PMID 26919719, 2016). "Both associated demyelinating diseases develop seizures, however, they are more common in patients with MOG antibody-associated demyelination than in patients with AQP4 antibody-associated demyelination, which is thought to be related to cortical and subcortical lesions." (PMID 34681255, 2021). "In recent years, numerous studies have found that the MOG antibody (MOG-ab) was associated with some rare and atypical demyelination types, which may expand the spectrum of MOGAD, such as unilateral cerebral cortical encephalitis and meningitis." (PMID 33841310, 2021).
demyelination (continued). "Most investigated lesions (153 of 167 in total) showed an ADEM-like pattern of damage: the perivenous disseminated inflammatory demyelination, MOG-dominant myelin loss with preserved oligodendrocytes, CD4-dominant T cell infiltration, and perivascular MOG-laden macrophages." (PMID 33374173, 2020). "Collaborative international consensus to derive shared clinical evaluative platforms standardized biological and neuroimaging protocols which can be used clinically, and partnered research programs are required to advance personalized treatment for children with MOG-Ab-associated demyelination." (PMID 30671648, 2019). "However, antibody affinity remains to be defined in human MOG Ab-associated disorders, and larger MOG Ab epitope studies and their correlations with clinical phenotypes are warranted in both paediatric and adult demyelination." (PMID 31481127, 2019). "Pathological studies of myelin oligodendrocyte glycoprotein antibody-associated disease (MOGAD) have reported that MOG was expressed on the outermost layer of the myelin sheath of myelin where MOG resides, MOG antibody-associated demyelination may initially occur on the surface of the myelin sheath." (PMID 38646337, 2024). "Importantly, phenotypes which have recently been described as classical for MOG Ab-associated demyelination, such as children presenting with monophasic ADEM, UON, and BON, and adults presenting with relapsing UON and BON, were reported seronegative by fixed assays." (PMID 31481127, 2019). "Furthermore, 19 children and 28 adults, in whom therapeutic data was available, were highly sensitive and responsive to immunotherapy, particularly steroids, once again highlighting that these patients behave in a manner considered typical for MOG Ab-associated demyelination." (PMID 31481127, 2019). "In summary, our study points to a role of predominant humoral immunity and possible role of Th17 cells and neutrophils in MOG antibody associated demyelination, which strengthens the hypothesis that MOG antibody defines a separate immunopathological syndrome with dominant humoral autoimmunity." (PMID 26919719, 2016). "Antibodies to MOG are associated with CNS demyelination, whereas peripheral nervous system (PNS) demyelination is seldom reported to be related to MOG-IgG." (PMID 38930142, 2024). "In contrast, MOG IgG serological testing should only be performed in adults with demyelination in the context of a suspected clinical or radiological phenotype for MOGAD." (PMID 38783085, 2024). "An international study evaluating paired serum/CSF in 255 selected patients with demyelination reported 31 (12%) patients had CSF‐restricted MOG‐IgG, with 27/31 thought to have a potential phenotype for MOGAD, associated with higher disability at follow‐up." (PMID 39073255, 2024). "As in MS and MOG-EM/MOGAD, ON in NMOSD was associated with prolonged P100 latencies caused by demyelination both in AQP4-IgG-positive and in mixed, AQP4-IgG-positive and AQP4-IgG-negative cohorts." (PMID 37022481, 2023). "Spinal cord sections of MOG–EAE mice (model of chronic MS) showed marked demyelination that was largely improved by i.n. anti-HuR ASO treatment." (PMID 36696009, 2023). "This limitation should continue to resolve with increased recognition of MOGAD and availability of MOG‐Ab testing as part of the initial clinical evaluation of demyelination." (PMID 37000895, 2023). "In this article, we aim to review all current knowledge on the immunopathology of TDL with emphasis on biopsy-proven MS-, NMO-, NMOSD-, and MOG-related demyelination." (PMID 35418930, 2022). "First, in a MOG-induced EAE mouse model of demyelination, we performed clinical neurological function scores and body weight monitoring for 40 days." (PMID 36482934, 2022). "Since we found that OMGP-specific T cells open the blood–brain barrier and paved the way for anti-MOG mediated demyelination, we also injected OMGP-specific mAbs together with OMGP-specific T cells." (PMID 33256847, 2020).